MTMR8 (myotubularin related protein 8)
Description:
Lipid phosphatase that specifically dephosphorylates the D-3 position of phosphatidylinositol 3-phosphate and phosphatidylinositol 3,5-bisphosphate, generating phosphatidylinositol and phosphatidylinositol 5-phosphate. In complex with MTMR9, negatively regulates autophagy.
Synonyms: FLJ20126
Tractability: PROTAC: ubiquitination databases record sites on it.
Gene: Protein-coding gene on chromosome X (64,268,081 to 64,395,452, reverse strand). Ensembl gene ENSG00000102043.
Subcellular location: Nucleus envelope
Pathways (Reactome):
Metabolism: Synthesis of PIPs at the plasma membrane
Gene Ontology:
Molecular function: phosphatidylinositol-3,5-bisphosphate 3-phosphatase activity; phosphatidylinositol-3-phosphate phosphatase activity; protein binding; phosphatidylinositol-3,5-bisphosphate phosphatase activity
Biological process: regulation of macroautophagy; phosphatidylinositol dephosphorylation; phosphatidylinositol metabolic process
Cellular component: cytoplasm; nuclear envelope; cytosol
Homologues: Orthologues: chimpanzee MTMR8 (99% identical), macaque MTMR8 (97% identical), pig MTMR8 (85% identical), rabbit MTMR8 (84% identical), tropical clawed frog asb12.2 (54% identical), zebrafish mtmr8 (50% identical), Drosophila melanogaster Mtmr6 (42% identical), Caenorhabditis elegans mtm-6 (34% identical), Caenorhabditis elegans mtm-3 (23% identical), Drosophila melanogaster CG3632 (23% identical). Paralogues in human: MTMR6 (49% identical), MTMR7 (49% identical), MTMR2 (30% identical), MTM1 (30% identical), MTMR1 (30% identical), MTMR3 (28% identical), MTMR4 (28% identical), MTMR9 (24% identical), SBF2 (23% identical), SBF1 (23% identical), MTMR10 (18% identical), MTMR12 (17% identical), and 1 more.
Diseases named in the same sentence as MTMR8 in open-access papers:
MTMR8 is named in the same sentence as 4 diseases in open-access papers, as found by Europe PMC text mining. Sharing a sentence is not in itself a finding about the gene and the disease. The quoted sentences say what the papers report.
anxiety disorder (1 paper, 2017). A category of psychiatric disorders which are characterized by anxious feelings or fear often accompanied by physical symptoms associated with anxiety. "A 279 kb deletion in Xq11.2 encompassing the gene MTMR8 was found in a patient with EO-OCD as well as in his mother and brother, who both suffer from anxiety disorder." (PMID 29179725, 2017).
leiomyoma (1 paper, 2023). A well-circumscribed benign smooth muscle neoplasm characterized by the presence of spindle cells with cigar-shaped nuclei, interlacing fascicles, and a whorled pattern. "This analysis indicated that the expression of WNT16, CACNA1D, DCX, and WIF1 was significantly higher, while the expression of MTMR8 was significantly lower in myometrium adjacent to MED12-mutated leiomyomas compared to myometrium adjacent to MED12 wild-type leiomyomas." (PMID 36835153, 2023).
MTMR8 also shares sentences with these, for which no sentence is quoted: cancer (1 paper); Myotubular myopathy (1).